KLF12 (KLF transcription factor 12)
Diseases named in the same sentence as KLF12 in open-access papers (continued):
Sharing a sentence is not in itself a finding about the gene and the disease.
pancreatic cancer (10 papers, 2016 to 2025). "In addition, further characterization of the chr13q22.1 locus found a single nucleotide polymorphism (SNP) mutation in a gene desert closest to both KLF5 and KLF12 that was significantly correlated with a higher risk of pancreatic cancer." (PMID 37239940, 2023). "Our results suggest that miR-137 reduces stemness features of pancreatic cancer cells by Targeting KLF12-associated Wnt/β-catenin pathways and may identify new diagnostic and therapeutic targets in pancreatic cancer." (PMID 30866999, 2019). "In pancreatic cancer specimens, the levels of KLF12 positively correlated with genes activated by the WNT/β-catenin pathway." (PMID 37239940, 2023). "In our study, we found that miR-671-3p was significantly downregulated in TAMs, inhibited M2 macrophage polarization and attenuated pancreatic cancer cell proliferation and metastasis by directly targeting KLF12." (PMID 35526050, 2022). "Herein, we demonstrated that KLF12 as the target of miR-137 induced activation of wnt/β-catenin promotes the stemess of pancreatic cancer cells." (PMID 30866999, 2019). "In order to explore the function and downstream signal pathways of KLF12, combining with the TCGA pancreatic cancer data set analysis, our results revealed that KLF12 was significantly correlated with activation of the Wnt/β-catenin signaling pathway." (PMID 30866999, 2019). "To explore potential targets through which miR-137 inhibits the CSC phenotype in pancreatic cancer cells, we searched publicly available algorithms (miRanda and TargetScan) and identified KLF12." (PMID 30866999, 2019). "The activity of Wnt/β-catenin signaling and expression of downstream molecules was significantly decreased in miR-137-overexpress and KLF12-downregulated pancreatic cancer cells, but was increased in miR-137-inhibited cells." (PMID 30866999, 2019). "Next, we investigate the clinical relevance between KLF12 level and canonical Wnt pathway in human pancreatic cancer specimens." (PMID 30866999, 2019). "In order to study the molecular biological mechanism involving miR-137, and target gene KLF12 regulating pancreatic cancer cell stemness." (PMID 30866999, 2019). "In summary, we have identified for the first time that the microRNA-137 reduces stemness features of pancreatic cancer cells by targeting KLF12 inhibit Wnt/β-catenin signaling pathway." (PMID 30866999, 2019). "GWAS have also identified a pancreatic cancer risk locus in the region between KLF5 and KLF12 (refs 34, 35, 36)." (PMID 27117709, 2016). "Additionally, miR-671-3p inhibition has been shown to promote macrophage M2 polarization via the KLF12/AKT/c-myc signaling pathway in pancreatic cancer." (PMID 39748408, 2025). "In addition, DVL2/WNT/β-catenin axis has been identified as a driver of progression mediated by KLF12 in pancreatic cancer." (PMID 41135528, 2025). "KLF12-positive TAMs increase pancreatic cancer cell proliferation, migration, and invasion." (PMID 37239940, 2023). "Next, we found that KLF12+ TAMs could enhance the ability of pancreatic cancer cell proliferation, invasion and migration." (PMID 35526050, 2022). "Together, these results indicated that LncRNA-PACERR could release KLF12 by sequestering miR-671-3p, thereby achieving TAMs to facilitate malignant progression of pancreatic cancer via the KLF12/AKT/c-myc pathway." (PMID 35526050, 2022). "KLF12 as miR-137 target inhibits CSC phenotype in pancreatic cancer cells." (PMID 30866999, 2019). "Therefore, our findings reveal a novel mechanism for activation of wnt/β-catenin pathway involving miR-137/KLF12 in pancreatic cancer." (PMID 30866999, 2019). "Therefore, we propose that miR-137 inhibits pancreatic cancer stemness properties and tumorigenicity by targeting KLF12 via preventing nuclear translocation of β-catenin and activation of Wnt signaling." (PMID 30866999, 2019).
pancreatic cancer (continued). "Taken together, our findings further supported the notion that elevated KLF12 expression activates canonical Wnt pathway through transcriptional regulating Dvl2, which subsequently prevents β-catenin degradation and promotes β-catenin translocated to the nucleus in pancreatic cancer." (PMID 30866999, 2019). "We proved that LncRNA-PACERR promotes malignant progression of pancreatic cancer through two pathways: as ceRNA sponging miR-671-3p to activate the KLF12/AKT/c-myc pathway and interacting with IGF2BP2 to enhance KLF12 and c-myc stability." (PMID 35526050, 2022). "KLF12 is increased in pancreatic cancer specimens compared to normal adjacent tissue and positively regulated by circ_0005273 and LncRNA-PACERR." (PMID 37239940, 2023). "KLF12 has been extensively studied in pancreatic cancer and can promote pancreatic cancer malignant progression via AKT/c-myc axis, which has not been reported in TAMs." (PMID 35526050, 2022). "Thus, our overall results suggest that miR-137 and KLF12 effectively interact to suppress CSC formation and proliferation in human pancreatic cancer cells." (PMID 30866999, 2019). "Further exploration of the upstream molecular events modulating the miR-137/KLF12 interaction, and the resulting impact on Wnt/β-catenin signaling-mediated CSC induction, might shed new light on pancreatic cancer development and progression." (PMID 30866999, 2019). "KLF12 expression correlates with DVL2 and canonical Wnt pathway in clinical pancreatic cancer." (PMID 30866999, 2019).
lung carcinoma (7 papers, 2016 to 2024). "Reduced expression levels of KLF12 results in increased ability of lung cancer cells to form tumours in vivo and is associated with poorer survival in lung cancer patients." (PMID 26455320, 2016). "As expected, shorter PFS and OS were observed in lung cancer patients with high expression of PD‐L1, as well as high expression of KLF12." (PMID 37606530, 2023). "In this study, we found that KLF12 is significantly correlated with PD‐L1 expression in non‐small cell lung cancer (NSCLC) patient tumor tissues." (PMID 37606530, 2023). "Here, we found that KLF12 expression was significantly higher in non‐small cell lung cancer (NSCLC) cells with higher programmed death‐ligand 1 (PD‐L1) expression." (PMID 37606530, 2023). "Overexpression of KLF12 in endometrial and lung cancer cell lines correlated with increased cellular proliferation, decreased apoptosis, and increased in vivo tumor growth." (PMID 33937014, 2021). "In some cases, KLF12 was overexpressed and served as a tumor suppressor, for example, in bladder cancer and lung cancer." (PMID 34950609, 2021). "We report here that expression of KLF12, a member of the Kruppel-like family of transcription factors, is downregulated in lung cancer cell lines that have been selected to grow in the absence of cell adhesion." (PMID 26455320, 2016). "Tail-vein assays confirmed the role of KLF12 as a suppressor of metastatic colony formation and higher expression levels of KLF12 correlate with increased survival of lung cancer patients in clinical data sets." (PMID 26455320, 2016). "Knocking down KLF12 results in increased survival of lung cancer cells growing in suspension as well as increased tumour formation in a mouse experimental metastasis model." (PMID 26455320, 2016). "As a new metastasis suppressor gene, KLF12 after knockout might reduced the apoptosis of lung cancer cells, and could promote S-phase cell cycle transition or regulate the anoikis." (PMID 38560274, 2024). "Furthermore, a recent study reported that KLF12 is a novel metastasis-suppressor gene and suppression of KLF12 resulted in anoikis resistance in lung cancer cells." (PMID 28095864, 2017). "This is important, due to KLF12 is able to regulate cell death, by promoting the cell cycle transition through S phase and therefore cell proliferation and reduced expression levels of KLF12 results in increased ability of lung cancer cells to form tumors in vivo." (PMID 35444536, 2022). "Moreover, low KLF12 expression levels correlate with reduced survival in lung cancer patients." (PMID 26455320, 2016). "In this paper, KLFs have been summarized via systematic reviews, with either a promoting (KLF4 ∼ KLF8, KLF15) or an inhibiting (KLF2 ∼ KLF6, KLK9 ∼ KLF12 and KLF17) roles, which should be useful to monitor lung cancer progression or understand its mechanisms." (PMID 38560274, 2024). "Thus KLF12 could act as a potential tumour suppressor in lung cancer." (PMID 26455320, 2016).
breast carcinoma (6 papers, 2020 to 2025). "Many genes are involved in the development of breast cancer, including the Kruppel Like Factor 12 (KLF12) gene, which has been implicated in the development and progression of several cancers." (PMID 37156774, 2023). "In this study, we examined the role of KLF12 in breast cancer and its associated molecular mechanisms." (PMID 37156774, 2023). "This study examined the role of KLF12 in breast cancer and its associated molecular mechanisms." (PMID 37156774, 2023). "KLF12 has already been reported to repress gene expression by binding to gene promoter regions and offer a potential diagnostic biomarker and therapeutic treatment for basal-like breast carcinoma." (PMID 33820555, 2021). "In the xenotransplantation experiment, the tumorigenicity of breast cancer cells was found to decrease when KLF12 expression in the cells was knocked down." (PMID 37156774, 2023). "To further investigate the role of KLF12 in breast cancer, we first examined the protein levels of KLF12 in breast cancer cells (MCF-7, ZR-75-30, T47D, and MDA-MB-231)." (PMID 37156774, 2023). "Next, the effect of KLF12 on the growth and tumorigenesis of breast cancers was determined by evaluating its effect on the viability of the cells using an MTT assay." (PMID 37156774, 2023). "Our data revealed a positive effect of KLF12 on breast cancer proliferation, cell cycle, and apoptosis." (PMID 37156774, 2023). "Previous studies have also shown that circ-NOTCH3 and the long non-coding RNA NEAT1 can promote breast cancer development by up-regulating KLF12 expression." (PMID 37156774, 2023). "To further investigate the role of KLF12 in the proliferation of breast cancer cells, we carried out extensive experiments." (PMID 37156774, 2023). "Human breast cancer xenograft mouse model was constructed to further investigate the role of KLF12 in tumorigenesis." (PMID 37156774, 2023). "KLF12 was found to promote the proliferation of breast cancer and inhibit apoptosis in response to genotoxic stress." (PMID 37156774, 2023). "More recently, it has been shown that miR-205 directly targets Krüppel-like factor 12 (KLF12) to reduce the progression of breast cancer (BC) basal-like malignances." (PMID 33375067, 2020). "Similarly, circ_NOTCH3 interacts with miR-205 and targets KLF12, leading to the downregulation of KLF12 expression in basal-like breast cancer cells." (PMID 41001034, 2025). "In conclusion, our datas suggest that KLF12 could inhibit p21 transcription in breast cancer through two pathways." (PMID 37156774, 2023). "Collectively, these results suggested that KLF12 might have an important role in promoting growth and inhibiting apoptosis in breast cancer cells." (PMID 37156774, 2023). "The results showed that KLF12 could promote the proliferation of breast cancer cells and inhibit the apoptosis of cancer cells treated with CDDP." (PMID 37156774, 2023). "More recently, the tumor suppressor microRNA-205 has been reported to directly target KLF12 and inhibit the invasion and apoptosis of basal-like breast carcinoma (BLBC), suggesting that KLF12 may be a potential biomarker of BLBC." (PMID 37156774, 2023).
breast carcinoma (continued). "Collectively, the results suggested that KLF12 could promote the growth of breast cancer cells." (PMID 37156774, 2023). "Previous studies have shown that KLF12 may have an important role in breast cancer." (PMID 37156774, 2023). "Thus, exploring the molecular mechanism of KLF12 in breast cancer may provide new information for improving breast cancer treatment." (PMID 37156774, 2023). "In addition, through Expression Data Analysis, Rajeswary and coworkers have verified KLF12 as a potential target for controlling breast cancer development without harming pregnancy and the fetal developmental process." (PMID 37156774, 2023). "However, the comprehensive regulatory network of KLF12 in breast cancer has not yet been fully elucidated." (PMID 37156774, 2023).
osteosarcoma (5 papers, 2017 to 2021). A usually aggressive malignant bone-forming mesenchymal neoplasm, predominantly affecting adolescents and young adults. "Also, circ_0003496 enhanced tumorigenesis and chemoresistance in osteosarcoma by regulating KLF12 via absorbing miR-370." (PMID 34616917, 2021). "miR-382 overexpression restrained osteosarcoma cell proliferation and chemoresistance by regulating HIPK3 and KLF12." (PMID 29113367, 2017).
colon cancer (4 papers, 2014 to 2023). "To conclude, we identified two distinct qPCR gene expression profiles correlating with response (low expression of ALDH6A1 + TFF2 + MCM5) and with PFS (KLF12-high + TFF2-low) in advanced colon cancer patients managed with bevacizumab and chemotherapy." (PMID 24555920, 2014). "We generated CRISPR/Cas9‐mediated knockout (KO) of negative control (NC) and Klf12 in mouse colon cancer CT26 cells, and we also generated KO of Klf8 as a control." (PMID 37606530, 2023).
endometrial cancer (4 papers, 2014 to 2023). Primary or metastatic malignant neoplasm involving the endometrium (mucous membrane that lines the endometrial cavity). "As a transcription factor, overexpression of KLF12 in endometrial cancer cell lines significantly repressed proliferation and secretion of pro-survival factors such as insulin-like growth factor binding protein-1." (PMID 24555920, 2014).
small cell lung carcinoma (4 papers, 2020 to 2023). Small cell lung cancer (SCLC) is a highly aggressive malignant neoplasm, accounting for 10-15% of lung cancer cases, characterized byrapid growth, and early metastasis. "Small cell lung cancer-derived exosomal miR-141 induced neovascularization through targeting Kruppel-like factor 12 (KLF12)." (PMID 35592419, 2022). "Likewise, in small cell lung cancer (SCLC), miR-141 promotes angiogenesis via the KLF12 pathway." (PMID 36158660, 2022).
nasopharyngeal carcinoma (3 papers, 2020 to 2023). A carcinoma arising from the nasopharyngeal epithelium. "In nasopharyngeal carcinoma, hsa-miR-1207 has been shown to be inhibited by non-coding RNA Pvt1 or long non-coding RNA 319, which may act as a sponge to miRNAs, inducing cellular proliferation via PI3K/AKT, or carcinogenesis via KLF12 signaling pathways, respectively." (PMID 38146340, 2023).
asthma (2 papers, 2024 to 2025). "For an in vitro model of asthma, KLF12 overexpression suppresses LPS-induced inflammatory response and oxidative stress." (PMID 41105618, 2025).
bipolar disorder (2 papers, 2013 to 2015). A disorder of the brain that causes unusual shifts in mood, energy, activity levels and the ability to carry out day-to-day tasks. "Considering the gene KLF12 as input, since it is mentioned as one of the most important gene related to bipolar disorders, the ontological enrichment using the Wang similarity measure with a threshold of 0.3 returns a large set of 532 genes that belong to similar GO biological processes." (PMID 23369106, 2013).
bladder cancer (2 papers, 2021 to 2024). "This interaction is negatively regulated by KLF12 and plays a tumour suppressor role in bladder cancer (BC) cells." (PMID 39061144, 2024).
cervical (2 papers, 2020 to 2021). "Thus, KLF12 may play a major role in the underlying mechanisms that lead to hrHPV infection, persistence and cervical carcinogenesis." (PMID 33225922, 2020).
cervical squamous cell carcinoma (2 papers, 2021 to 2023). A squamous cell carcinoma arising from the cervical epithelium. "The decreased expression of KLF12 was observed in the nucleus of both cervical squamous cell carcinoma tissue and adenocarcinoma tissue." (PMID 36983713, 2023). "Decreased expression of KLF12 was observed in the nucleus of both cervical squamous cell carcinoma tissue and adenocarcinoma tissue." (PMID 34950609, 2021).
cervical tumor (2 papers, 2021 to 2025). "In our study, it is found that KLF12 was mainly distributed in the nucleus with a reduced expression in cervical tumor tissues according to HPA database." (PMID 34950609, 2021). "However, integrated HPV31 genomes from several cervical tumors overlap integration hotspots, including those on chromosomes 3 and 17 that contain the KLF5/KLF12 and KRT9/KRT14 genes, respectively." (PMID 40892869, 2025).
diabetes (2 papers, 2018 to 2019). "Both meta-analyses presented consistent tests of DGE and the results showed that genes of ACADSB, RASSF2, and KLF12 had significant gene expression associations with diabetes traits." (PMID 29503662, 2018). "The analysis showed that six gene sets and three member genes of ACADSB, RASSF2, and KLF12 had significant associations with diabetes traits." (PMID 29503662, 2018). "In total, of the top five association signals that were mapped to genes (n = 103) we found five (CDKAL1, DCDC2C, KLF12, LPIN2, TLE1) to be related with diabetes." (PMID 31818369, 2019).
endometriosis (2 papers, 2015 to 2022). The growth of functional endometrial tissue in anatomic sites outside the uterine body. "We recently found that KLF12 was markedly up-regulated in endometrium from endometriosis and RIF patients (unpublished data), and we will further investigate the expression patterns of miR-181a in these patients to better understand the role miR-181a plays in the pathogenesis of these diseases." (PMID 25889210, 2015).
esophageal adenocarcinoma (2 papers, 2016 to 2026). A malignant tumor with glandular differentiation arising predominantly from Barrett mucosa in the lower third of the esophagus. "Recently, genome-wide analysis showed that KLF12 amplification was found in about 40% of esophageal adenocarcinoma (EAC) cases and in 45% of salivary tumors." (PMID 27442508, 2016).
head and neck cancer (2 papers, 2016 to 2020). A primary or metastatic malignant neoplasm affecting the head and neck. "KLF12 has been linked to several cancers, including head and neck cancers, which are usually associated with hrHPV." (PMID 33225922, 2020). "KLF12 has previously been reported to have an oncogenic role in gastric and head and neck cancers, although other studies suggest KLF12 might have a tumour-suppressive role." (PMID 26455320, 2016).